ANKHD1 (ankyrin repeat and KH domain containing 1)
Diseases named in the same sentence as ANKHD1 in open-access papers (continued):
Sharing a sentence is not in itself a finding about the gene and the disease.
cancer (continued). "Whilst the function of ANKHD1 initially appeared to be independent of cancer types, more recent studies have suggested that different transcript variants of ANKHD1 may confer different roles at both cellular and clinical levels." (PMID 37629022, 2023). "However, most of the cancers do not show a significant change in ANKHD1 mRNA or mutation status in the cancer samples compared to the healthy tissue samples." (PMID 37629022, 2023). "The initial category, containing ANKHD1, ATXN8OS, HSPB8, LSM7, MAFB, and TCTN2, is involved in the direct regulation of cancer cell proliferation, apoptosis, and cancerization." (PMID 34235216, 2021). "In addition, siRNA-mediated silencing of all transcripts of eight genes that showed a consistent differential splicing signature across multiple cancer types (ABCC5, ANKHD1, DYNLL1, F8, RPL31, TMEM14C, UQCC, and CRNDE) failed to reveal differences in cell viability." (PMID 25424858, 2015).
tumor (7 papers, 2019 to 2023). "The associationship between ANKHD1 expression and tumor metastasis, ANKHD1 protein levels were detected by immunohistochemistry (IHC)." (PMID 36171217, 2022). "Consistently, ANKHD1 positivity was significantly associated with large tumor size, microvascular invasion, multiple nodules, poor tumor differentiation, high TNM stage, and most importantly, shorter overall survival and recurrence-free survival." (PMID 33637115, 2021). "Positive expression of ANKHD1 was significantly associated with large tumor size, microvascular invasion, multiple nodules, poor tumor differentiation, and high TNM stage." (PMID 30646949, 2019). "In all three studies, increased expression of ANKHD1 is associated with greater tumour growth, metastasis, larger tumours, and more nodules (abnormal tissue growths greater than 1 cm in diameter), resulting in poorer prognosis, more aggressive growth, and a decrease in patient prognosis." (PMID 37629022, 2023). "Furthermore, at a clinical level, the increased expression of ANKHD1 has been associated with greater tumour infiltration, increased metastasis, and larger tumours." (PMID 37629022, 2023). "Higher levels of ANKHD1 are correlated with larger tumours, more nodes, poorer differentiation of tumour boundaries, more advanced metastasis, shorter time between recurrence and overall reduced survival rates." (PMID 37629022, 2023). "Therefore, our data reveal a new mechanism for ANKHD1 in promoting tumor progression, serving as a “reader” protein coordinating with SMYD3 to promote target gene expression." (PMID 30646949, 2019). "Decreased expression of ANKHD1 was observed in tumor sections from the sh-ANKHD1 group with or without IR, and increased γH2AX expression was observed post IR." (PMID 35110552, 2022). "Notably, the expression patterns of ANKHD1 and MYO1C transcripts differ between the cell lines, indicating that they are indeed specific for different stages of tumour progression." (PMID 31443305, 2019). "However, whether ANKHD1 could bind a specific histone mark and serve as an tumor promoter in HCC is not yet known." (PMID 30646949, 2019). "Thus, both ANKHD1 and FZD6 have well-characterized tumor cell-intrinsic roles, however, how they mediate their role in regulating tumor cell- extrinsic metastasis is not clear." (PMID 32245826, 2020).
ANKHD1 also shares sentences with these, for which no sentence is quoted: uterine corpus endometrial carcinoma (2 papers); acute myeloid leukaemia (1); atherosclerosis (1); autosomal dominant polycystic kidney disease (1); dementia (1); non-small cell lung carcinoma (1); papillary carcinoma (1); renal carcinoma (1); stomach adenocarcinoma (1).